OR1Q1 (olfactory receptor family 1 subfamily Q member 1)
Description:
Odorant receptor.
Synonyms: OR9-A; OR1Q2; OR1Q3; OST226; HSTPCR106; OST226OR9-A; TPCR106; OR9-25
Tractability: Antibody: UniProt places it where antibodies can reach, with medium confidence; UniProt predicts a signal peptide or a membrane-spanning region; its Gene Ontology location is reachable by antibodies, with medium confidence.
Gene: Protein-coding gene on chromosome 9 (122,614,738 to 122,615,682, forward strand). Ensembl gene ENSG00000165202.
Subcellular location: Cell membrane
Pathways (Reactome):
Sensory Perception: Expression and translocation of olfactory receptors
Gene Ontology:
Molecular function: olfactory receptor activity; G protein-coupled receptor activity
Biological process: sensory perception of smell; signal transduction; detection of chemical stimulus involved in sensory perception of smell; G protein-coupled receptor signaling pathway
Cellular component: membrane; plasma membrane
Genetic constraint (gnomAD): Loss-of-function variants: 0 observed, 0.44 expected, observed/expected ratio (o/e) 0, 90% interval 0 to 1.84. That is too few expected variants to judge how well the gene tolerates losing a copy. Missense variants: 360 observed, 401.6 expected, observed/expected ratio (o/e) 0.9, 90% interval 0.82 to 0.98. Synonymous variants: 149 observed, 148.34 expected, observed/expected ratio (o/e) 1, 90% interval 0.88 to 1.15.
Homologues: Orthologues: chimpanzee OR1Q1 (99% identical), macaque OR1Q1 (94% identical), rabbit OR1Q1 (82% identical), mouse Or1q1 (80% identical), rat Or1q1 (76% identical). Paralogues in human: OR1F1 (49% identical), OR1L6 (49% identical), OR1L1 (49% identical), OR1J1 (48% identical), OR1J4 (48% identical), OR1N2 (48% identical), OR1L4 (48% identical), OR1C1 (48% identical), OR1G1 (47% identical), OR1J2 (47% identical), OR7A5 (47% identical), OR7D4 (47% identical), and 116 more.